FGF23 (fibroblast growth factor 23)
Diseases named in the same sentence as FGF23 in open-access papers (continued):
Sharing a sentence is not in itself a finding about the gene and the disease.
chronic kidney disease (continued). "Chronic Kidney Disease (CKD) is possibly the most common cause of elevated FGF23, which has been implicated in increased cardiovascular mortality of CKD patients." (PMID 30192823, 2018). "Patients with advanced chronic kidney disease (CKD) typically exhibit secondary hyperparathyroidism associated with high serum FGF23, high serum phosphate, and low 1,25(OH)2D levels." (PMID 28094278, 2017). "Multivariable-adjusted associations between natural log-transformed fibroblast growth factor-23 and natural log-transformed markers of inflammation in the overall sample and by chronic kidney disease (CKD) status." (PMID 25811862, 2015). "Fibroblast growth factor 23 (FGF23) plays a central role in mineral and bone disorders associated with chronic kidney disease (CKD-MBD)." (PMID 24885942, 2014). "Disruption of FGF23-α-KL signaling is thought to be an early hallmark of chronic kidney disease (CKD) involving reduced renal α-KL expression and a reciprocal rise in serum FGF23." (PMID 24466013, 2014). "High levels of FGF23 are associated with increased mortality in the chronic kidney disease (CKD) population." (PMID 24373521, 2013). "In chronic kidney disease, elevated levels of fibroblast growth factor 23 inhibited PDE4B expression in cardiomyocytes, further increasing sarcoplasmic reticulum Ca2+ leakage as well as promoting ventricular arrhythmias." (PMID 41602587, 2026). "Carotid intima-media thickness, FGF-23, and mineral bone disorder were analyzed in a cross-sectional study on 42 children aged 2–18 years old with chronic kidney disease stages 2 to 5D." (PMID 40136613, 2025). "Serum FGF-23 levels increase early during chronic kidney disease progression before changes in other parameters of bone and mineral metabolism." (PMID 40136613, 2025). "The Chronic Renal Insufficiency Cohort (CRIC) study showed FGF23 was a stronger predictor of mortality than established cardiovascular risk factors." (PMID 41561945, 2025). "It is believed that low KLOTHO protein concentration, combined with very high FGF23 concentrations and hyperphosphatemia, is partly responsible for adverse changes in the circulatory system in patients with chronic kidney disease." (PMID 41008628, 2025). "The effect of FGF23 is reduced by the decrease in Klotho protein in patients with chronic kidney disease (CKD)." (PMID 41426862, 2025). "Chronic kidney disease (CKD) causes a dysregulation of the parathyroid hormone (PTH), fibroblast growth factor 23 (FGF23) and vitamin D homeostasis, which induces abnormalities of calcium and phosphate metabolism." (PMID 40141345, 2025). "Yet, in chronic kidney disease, there is a development of resistance to FGF-23 signaling, so PTH is persistently elevated, contributing to secondary hyperparathyroidism (SHPT)." (PMID 40564142, 2025). "FGF23 plays a crucial role in the pathophysiology of disorders like chronic kidney disease and various bone-related conditions." (PMID 41394119, 2025). "Fibroblast growth factor 23 (FGF23) is markedly elevated in patients with chronic kidney disease, especially those receiving maintenance dialysis." (PMID 40464156, 2025). "It has been hypothesized that acute kidney injury (AKI), in contrast to chronic kidney disease (CKD), may be associated with increased FGF23 cleavage, resulting in a decreased ratio of intact to C-terminal FGF23 (iFGF23:cFGF23)." (PMID 40869274, 2025). "Chronic kidney disease (CKD) is a common condition associated with early and strong surges in plasma FGF23 levels." (PMID 39887469, 2025). "Active inducers of VC in chronic kidney disease include hypercalcemia, hyperphosphatemia, abnormal iPTH levels, FGF-23, uremic toxicity, and inflammation." (PMID 40136613, 2025). "The aim of this work was to investigate the efficacy of physical exercise in chronic kidney disease by describing its impact on the Klotho-FGF23 axis." (PMID 38169578, 2024).
chronic kidney disease (continued). "Fibroblast growth factor 23 (FGF23), a major phosphate-regulating hormone, is elevated in individuals with chronic kidney disease." (PMID 38577264, 2024). "Elevated FGF-23 is an independent risk factor for end-stage renal disease in patients with relatively preserved kidney function and for mortality across the spectrum of chronic kidney disease (CKD)." (PMID 38711510, 2024). "Serum FGF23 has been shown to be increased in both early stages of chronic kidney disease as well as in early stages of acute kidney injury." (PMID 38361581, 2024). "Fibroblast growth factor 23 (FGF-23) and other markers of chronic kidney disease–mineral and bone disorder (CKD-MBD) provide valuable insights into disease processes, treatment options and patient prognosis." (PMID 39070948, 2024). "Elevated FGF23 levels are prevalent in kidney patients and are associated with poor outcomes and complications in both CKD and end-stage renal disease (ESRD) patients." (PMID 38791495, 2024). "Patients with autosomal dominant polycystic kidney disease (ADPKD) have disproportionately high levels of fibroblast growth factor 23 (FGF-23) for their chronic kidney disease stage, however only a subgroup develops kidney phosphate wasting." (PMID 37985930, 2024). "At present, FGF23 represents an interesting biomarker in conditions such as chronic kidney disease (CKD), where secondary hyperphosphatonism, despite being an adaptive mechanism, has negative effects on the body." (PMID 38634076, 2024). "Chronic kidney disease (CKD) is known to cause an increase in fibroblast growth factor 23 (FGF23)." (PMID 39176315, 2024). "The aim of this study was to investigate the efficacy of physical exercise in chronic kidney disease, describing its impact on the Klotho-FGF23 axis." (PMID 38169578, 2024). "One study reported an increase in LCN2 in chronic kidney disease and left ventricular hypertrophy along with increased fibroblast growth factor 23 (FGF23)." (PMID 38673873, 2024). "In chronic kidney disease (CKD), serum levels of intact FGF23 are highly elevated and associated with pathologic cardiac remodeling and cardiovascular mortality, including in dialysis patients." (PMID 39452290, 2024). "Patients with end-stage renal disease were assessed before and 28 months after KT using FGF23, PIP, and PTH serum concentrations and transthoracic echocardiography." (PMID 40115543, 2024). "For this reason, we conducted a systematic review of the evidence from randomized controlled trials (RCTs) investigating the efficacy of physical exercise in chronic kidney disease, describing its impact on the Klotho-FGF23 axis." (PMID 38169578, 2024). "From the analyzed studies, two presented the effects of resistance exercise in patients with stage 2 chronic kidney disease on the Klotho-FGF23 axis 29,30, maintenance of glomerular filtration rate (GFR) and bone mineral density (BMD)." (PMID 38169578, 2024). "Due to this function, it has long been known for its role in chronic kidney disease, characterized by elevated FGF23 levels and hyperphosphatemia." (PMID 36650549, 2023). "Further studies are required to fully elucidate the pathophysiological mechanisms underlying the association between circulating FGF23 and BMD in advanced-stage chronic kidney disease patients." (PMID 36836085, 2023). "In recent years, fibroblast growth factor 23 (FGF23) has gained wide attention in many fields of medicine and has become a promising biomarker linking chronic kidney disease (CKD) with CV morbidity and mortality." (PMID 37371618, 2023). "Given that our lab and others have shown that FGF23 circulating levels are upregulated in several chronic inflammatory lung diseases and chronic kidney disease, FGF23 has been known to be a commonly used pro-inflammatory and prognostic marker." (PMID 37763754, 2023).
chronic kidney disease (continued). "The counter-regulatory effect of FGF-23 on the bone-kidney axis in chronic renal failure protects against hyperphosphatemia, vitamin D toxicity, and related soft-tissue calcifications." (PMID 37065752, 2023). "Of note, FGF23 levels are increased in chronic kidney disease even before changes in serum calcium, phosphorous, or PTH levels." (PMID 37627287, 2023). "In the early stages of chronic kidney disease (CKD), there is an increased FGF-23-to-klotho ratio which is associated with vascular calcification." (PMID 37441489, 2023). "In chronic kidney disease (CKD) FGF23 levels increase due to higher production, but also as the result of impaired cleavage and reduced excretion from the body." (PMID 36831276, 2023). "This is in agreement with the data from the general population showing that an increase in FGF23 constitutes one of the first detectable biomarkers of chronic kidney disease." (PMID 37627287, 2023). "As in patients with chronic kidney disease, FGF‐23 levels were found to be positively correlated with increasing serum phosphate levels." (PMID 38053473, 2023). "Fibroblast growth factor-23 (FGF-23) is a phosphaturic hormone used to monitor chronic kidney disease (CKD) in humans." (PMID 37889764, 2023). "Chronic kidney disease (CKD) risk factors, including fibroblast growth factor-23, a uremic toxin, angiotensin II, and transforming growth factor-β, have been reported to inhibit the expression of cardiac miRNA-30." (PMID 38074330, 2023). "Fibroblast growth factor-23 (FGF-23) is a biomarker for the monitoring of chronic kidney disease in humans." (PMID 37893926, 2023). "FGF23 expression is known to increase in response to inflammation and hypoxia, ultimately leading to chronic kidney disease (CKD)." (PMID 37626956, 2023). "FGF-23 levels rise gradually, often by a factor of 1,000, in end-stage renal disease (ESRD) to keep phosphate homeostasis stable." (PMID 36812096, 2023). "Investigations involving 3070 patients from the CRIC (Chronic Renal Insufficiency Cohort) study demonstrated a direct association between decreased GFR and increased FGF23 and LVH levels." (PMID 38255650, 2023). "Mouse studies have recently shown that lipocalin-2 mediates the expression of Fgf23 in osteoblasts and osteocytes in response to inflammation and in chronic kidney disease." (PMID 36157448, 2022). "Several studies investigated the role of fibroblast growth factor 23 (FGF23) in the regulation of renal phosphate excretion in chronic kidney disease (CKD)." (PMID 36615023, 2022). "In the early stage of chronic renal failure, FGF23 secretion is stimulated by an uncertain mechanism to maintain phosphorus balance, subsequently, leading to decreased 1,25(OH)2D3 synthesis and triggering secondary hyperparathyroidism." (PMID 35801203, 2022). "Recently, the scenario of possible biomarkers in chronic renal failure has been enriched by new players such as Fibroblast Growth Factor-23 (FGF-23) and Klotho." (PMID 35205271, 2022). "In patients with early stages of chronic kidney disease, FGF23 levels begin to increase early with eGFR values below 90 ml/min/1.73 m2 in both the adult and pediatric population." (PMID 36440231, 2022). "High serum levels of fibroblast growth factor 23 (FGF23) characterize chronic kidney disease (CKD) since its early stages and have been suggested to contribute to inflammation and cardiovascular disease." (PMID 36569120, 2022). "Although there were many studies focused on the regulation of elevated FGF23 in chronic renal failure, the conclusions were inconsistent." (PMID 35801203, 2022). "Plasma phosphate levels increase in moderate to advanced chronic kidney disease (eGFR < 60 mL/min/1.73 m2), driven by markedly increased blood levels of phosphate-regulating hormones such as fibroblast growth factor 23 and parathyroid hormone." (PMID 35477475, 2022).
chronic kidney disease (continued). "Fibroblast growth factor 23 (FGF23) is elevated in patients with chronic kidney disease and contributes to left ventricular hypertrophy (LVH)." (PMID 35559350, 2022). "Mediators identified as important in chronic kidney disease-related cardiac fibrosis include elevated fibroblast growth factor-23, lowered Klotho levels, and elevated phosphorus levels." (PMID 36140195, 2022). "Chronic kidney disease is characterized by low αKlotho and 1,25(OH)2D levels and elevated circulating FGF23." (PMID 36501215, 2022). "In the moderate and severe stages of chronic renal failure, abnormally elevated circulating FGF23 can lead to some complications, including myocardial hypertrophy, which is positively correlated with all-cause mortality." (PMID 35801203, 2022). "For instance, in a rat model of adenine-induced chronic kidney disease, treatment with quercetin improved renal function by reduction of oxidative stress factors, serum levels of fibroblast growth factor-23 (FGF23), and kidney inflammation." (PMID 36558167, 2022). "Third, fibroblast growth factor-23 (FGF-23) concentrations increase markedly in chronic kidney disease." (PMID 35162472, 2022). "High circulating levels of fibroblast growth factor-23 (FGF23) are associated with left ventricular hypertrophy as well as increased morbidity and mortality in patients suffering from chronic kidney disease." (PMID 35884995, 2022). "FGF-23 is an emerging novel and powerful risk factor of mortality and CV events in patients with CKD and end stage renal disease." (PMID 36014837, 2022). "It is also known that FGF23 is increased from the early stage in patients with chronic kidney disease." (PMID 36303091, 2022). "In parallel with declining kidney function and decreasing phosphate clearance, FGF23 levels will elevate further and be more than a thousand-fold higher in end-stage renal disease (ESKD), compared with normal value." (PMID 35966090, 2022). "Patients with advanced chronic kidney disease (CKD) usually display secondary hyperparathyroidism correlated with high levels of FGF23, phosphate, and a low level of 1,25(OH) 2D in serum." (PMID 36303091, 2022). "Expression of CYP27B2 is up and downregulated by parathormone (PTH) and fibroblast growth factor-23 (FGF-23) respectively in the context of chronic kidney disease and mineral bone disorder (CKD-MBD)." (PMID 35308556, 2022). "Fibroblast Growth Factor 23 (FGF23) has emerged as an important biomarker in chronic kidney disease (CKD)." (PMID 35629904, 2022). "An extensive review of the impact of chronic kidney disease on FGF23 is beyond the scope of this review and has been extensively reviewed recently." (PMID 35629904, 2022). "Decreasing FGF23 levels by inhibition of lipocalin-2 has been suggested as a therapeutic approach to improve outcomes in chronic kidney disease." (PMID 36157448, 2022). "In clinical medicine, the plasma FGF23 concentration has been revealed as a valuable disease biomarker which is positively correlated with progression and outcome in chronic kidney disease and further cardiovascular disorders." (PMID 34731356, 2022). "Chronic kidney disease (CKD) affects 10% of the world population and results in many patient complications, including iron deficiency and hyperphosphatemia, both potent stimulators of the phosphaturic hormone FGF23." (PMID 35656701, 2022). "We aimed to evaluate soluble Klotho and circulating fibroblast growth factor 23 (FGF23) ratio as a risk factor for renal progression, cardiovascular (CV) events, and mortality in chronic kidney disease (CKD)." (PMID 35872753, 2022). "The connection between FGF23 and phosphate serum levels has raised interest in investigating FGF23 as a potential marker for disturbed phosphate metabolism in chronic kidney disease (CKD) in humans, cats, and dogs." (PMID 36428422, 2022). "The present study found that FGF-23 was positively correlated with both previous heart failure and previous chronic renal failure." (PMID 36132198, 2022).
chronic kidney disease (continued). "Chronic kidney disease (CKD) is accompanied by increases in circulating fibroblast growth factor 23 (FGF23) and aldosterone levels." (PMID 33995120, 2021). "Several studies have pointed to serum levels of FGF-23 as predictors for renal outcomes and progression to end-stage renal disease in T2D patients." (PMID 34065223, 2021). "A growing number of clinical observations and experimental research involving animals shows that the FGF23 serum level increases significantly in chronic kidney disease much earlier than previously used biomarkers (creatinine, phosphates, vitamin D and PTH)." (PMID 34258392, 2021). "Excessively enhanced FGF23 concentrations of several hundred and up to several thousand pg/ml have been reported in both patients with end-stage renal disease and patients with end-stage heart failure." (PMID 32855522, 2021). "A prospective and case-cohort study involving chronic renal insufficiency patients monitored the FGF23 level at 2–5 years (mean, 4.0 ± 1.2 years) in a randomly selected sub-cohort of 1135 participants." (PMID 34069053, 2021). "In a small Polish study, in 37 children assessed with chronic kidney disease stage 3, median plasma FGF23 level ranged from 179 to 750 ng/L (1 ng/L = 1 pg/mL), while in the control healthy group, it was 55 ng/L (IQR, 30–108)." (PMID 34258392, 2021). "Increased fibroblast growth factor 23 (FGF23) is a risk factor for mortality, cardiovascular disease, and progression of chronic kidney disease." (PMID 33832449, 2021). "In our study investigating the mineral metabolism in end-stage renal disease, it was revealed that the sKl, 1,25(OH)2D and Ca levels decreased and FGF23, PTH and P levels increased in haemodialysis patients." (PMID 33776565, 2021). "It is believed that fibroblast growth factor 23 (FGF23) can become an early biomarker of chronic kidney disease progression." (PMID 34258392, 2021). "The expression of FGF23 has been found to be upregulated in bone disorders and chronic kidney disease as well." (PMID 34831463, 2021). "Cohort studies on end-stage renal disease patients with severe cardiac complications indicated enhanced serum levels of FGF23 and calcium." (PMID 34095143, 2021). "The high prevalence of heart failure is often seen in chronic kidney disease (CKD) patients, which is also associated with elevated levels of FGF23." (PMID 35265628, 2021). "Similar to FGF23- or αKlotho-deficient mice, patients with chronic kidney disease (CKD), which are typically characterized by high FGF23 levels and low αKlotho expression, suffer from the sequelae of hyperphosphatemia which drastically increase their cardiovascular mortality." (PMID 33517471, 2021). "FGF23 is considered as a marker of numerous conditions such as chronic kidney disease, in which osteocyte sclerostin and FGF23 are elevated." (PMID 32708317, 2020). "FGF23 increases to augment phosphaturia, which prevents phosphate accumulation at the early stages of chronic kidney disease (CKD)." (PMID 32188018, 2020). "FGF23 is a key factor in the pathogenesis of chronic kidney disease–metabolic bone disease, where significant increases in plasma FGF23 concentrations occur in humans, cats and dogs in parallel with the stages of kidney disease." (PMID 33027890, 2020). "The present review summarizes the complex regulation of FGF23 and the disturbed FGF23/Klotho system in chronic kidney disease (CKD)." (PMID 33233840, 2020). "Later, FGF23 was identified as a fundamental component of the mineral and bone disorder in chronic kidney disease (CKD) and has been the focus for extensive research." (PMID 33233840, 2020). "In patients with chronic kidney diseases, the production of FGF23 (intact FGF23) was separated from its cleaved form (C-terminal FGF23)." (PMID 33424930, 2020). "Elevated levels of FGF23 also cause acquired hypophosphatemic disorders, such as in tumor‐induced osteomalacia (TIO) and is an adaptive response in chronic kidney disease (CKD)." (PMID 33205007, 2020).